SLC9A1 (solute carrier family 9 member A1)
Diseases named in the same sentence as SLC9A1 in open-access papers (continued):
Sharing a sentence is not in itself a finding about the gene and the disease.
triple-negative breast carcinoma (10 papers, 2015 to 2021). An invasive breast carcinoma which is negative for expression of estrogen receptor (ER), progesterone receptor (PR), and human epidermal growth factor receptor 2 (HER2). "Accordingly, we observe reduced survival for patients suffering from luminal A or basal-like/triple-negative breast cancer with high SLC4A7 and/or low SLC9A1 mRNA expression." (PMID 34219652, 2021).
glioblastoma (7 papers, 2017 to 2023). The most malignant astrocytic tumor (WHO grade IV). "We further analyzed the data from the Ivy Glioblastoma Atlas Project in respect of SLC9A1 mRNA expression in the different regions of tumors." (PMID 30333031, 2018).
bladder cancer (5 papers, 2015 to 2022). "CDA involves in metabolic process, SLC9A1 is related with cancer growth, SLC24A4 had decreased expression in bladder cancer." (PMID 35033028, 2022). "The result showed that TERT was not expressed in normal bladder but overexpressed in bladder cancer with core promoter C228T mutation TERT; survival data of CDA, SLC9A1 and SLC24A4 also showed that their expression levels were associated with 5-year survival significantly." (PMID 35033028, 2022).
Hyperglycemia (4 papers, 2015 to 2022). An increased concentration of glucose in the blood. "SLC9A1 has been shown to be required for the increased adhesion, migration, and phagocytosis of oxidized LDL seen in monocytes in response to stimuli including leptin, adrenaline, and hyperglycemia." (PMID 31615550, 2019).
infertile (3 papers, 2016 to 2017). "Loss of only Slc9a1 or Slc9a3 in male mice induces infertility." (PMID 28384194, 2017).
Lichtenstein-Knorr syndrome (2 papers, 2015 to 2024). "SLC9A1 has been associated with Lichtenstein-Knorr syndrome (OMIM #616291), a recessive neurological disorder characterized by progressive cerebellar ataxia." (PMID 38519481, 2024).
mood disorder (1 paper, 2023). A cognitive disorder a disturbance in which the person's mood is hypothesized to be the main underlying feature. "Fluoxetine also normalises interstitial pH which is affected in mood disorders by phosphorylating and stimulating astrocytic Na+-H+ transporter NHE/SLC9a1." (PMID 37248211, 2023).
preeclampsia (1 paper, 2025). Preeclampsia is a hypertensive disorder of pregnancy that is characterized by new-onset hypertension with proteinuria presenting after 20 weeks of gestation, and depending on mild or severe forms may initially present with severe headache, visual disturbances, and hyperreflexia. "Cardiac gene expression of Vcam, Edn1, Ccr2, Ctgf, Tgfb1, Tgfb2, Tgfb3, Bnp, Cybb, Mmp2, Mmp9, Timp1, Camk2a, Slc9a1, Nr3c2, and Nr3c1 was not different between mice who had a normal pregnancy and mice who had a preeclampsia-like pregnancy at 5 or 10 weeks postpartum (respectively)." (PMID 40425613, 2025).
prostate neoplasm (1 paper, 2025). A neoplasm (disease) that involves the prostate gland. "Although the provided references do not directly address the association of prostate neoplasm with the ABCC5, HYAL2, and SLC9A1 proteins, it appears that the HMMR-rs299295 and STAB2-rs2271637 variants may play a role in the growth, proliferation, and metastasis of prostate neoplasm." (PMID 40567905, 2025).
cancer (159 papers, 2004 to 2026). A tumor composed of atypical neoplastic, often pleomorphic cells that invade other tissues. "The upregulation of SLC9A1 is positively associated with the level of immune infiltration and prognosis of cancer." (PMID 35041720, 2022). "Analysis of genetic alterations in TRPM4 and SLC9A1 across cancers was performed using the cBioPortal platform, encompassing 32 studies and 10, 967 samples." (PMID 41235237, 2025). "The sodium/hydrogen exchanger 1 (NHE1), encoded by the human SLC9A1 gene (solute carrier family 9A1), is the major H + efflux mechanism for maintaining the alkaline pHi of cancer cells." (PMID 37316699, 2023). "Surprisingly, results showed a downregulation of the SLC9A1 gene in tumor and metastatic groups compared to the non-cancer tissue." (PMID 36612049, 2022). "The Na+/H+ exchanger isoform 1 (NHE1, SLC9A1) is a major regulator of intracellular pH (pHi) and is widely explored as a target in cancer as well as in other diseases (see9,13)." (PMID 32242030, 2020). "Preclinical studies have shown pharmacological inhibition of SLC9A1 can amplify the anti-cancer effects of paclitaxel in MDA-MB-231 and MD-MB-468 cells." (PMID 32929364, 2020). "Sodium/hydrogen exchanger 1 (NHE1), encoded by the SLC9A1 gene (SoLute Carrier family 9A1) in humans, is the main H+ efflux mechanism in maintaining alkaline pHi in cancer cells." (PMID 30333031, 2018). "A similar pattern was observed after exposing cancer cell lines to hypoxia, which reduced SLC9A1-mediated H+ flux, whereas HCO−3 flux was hypoxia-insensitive." (PMID 24795638, 2014). "One popular model is that Na+/H+ exchangers, particularly NHE1 (SLC9A1), are the main reason for the reversal of pHi and pHe in cancer tissues, along with monocarboxylate-H+ efflux cotransporters MCT1 (SLC16A1) and MCT4 (SLC16A3) and carbonic anhydrases for CO2 hydration." (PMID 35787947, 2023). "Furthermore, we assessed the performance of two new small-molecule NaV1.5 inhibitors on the reduction of sodium currents, as well as showed that silencing SCN5A and SLC9A1 substantially reduced the 2D invasive capabilities of cancer cells." (PMID 36612049, 2022). "Moreover, they developed a protac for one of the best-behaved hits, SLC9A1 (or NHE1), a cancer-related Na+/H+ ion transporter with an important role in cytoplasmic and microenvironmental pH regulation." (PMID 33339292, 2020). "Even though there are far more types of acid-extruders than acid-loaders, piecewise knock-down of acid-extruders (SLC9A1, SLC4A7, or SLC16A3) can be sufficient to impair pHi control in cancer cells." (PMID 37999800, 2024). "These transporters, including the Na+/H+ exchanger NHE1 (SLC9A1) and the Na+, HCO3- cotransporters NBCn1 (SLC4A7) and NBCe2 (SLC4A5) confer additional advantages to the cancer cells, including stimulation of proliferation, survival, and invasiveness, leading to increased tumor growth and metastasis." (PMID 32457840, 2020). "Finally, inhibition of either SLC9A1 or HCO−3 transport attenuated spheroid growth, suggesting that both types of transporters are important for cancer cell survival and/or proliferation under 3D conditions." (PMID 24795638, 2014). "For example, SLC9A1 genetic ablation may not inhibit cell line growth under control conditions, yet significantly impairs cancer cell survival at low pHe." (PMID 37999800, 2024). "The conclusion here is that SLC9A1 could not accomplish the observed reversal of pHe and pHi because the Na+-in potential is considerably reduced in cancer due to the decreased ratio between intracellular and extracellular Na+ concentrations." (PMID 35787947, 2023).
tumor (138 papers, 2004 to 2026). "Missense mutations in SLC9A1 could disrupt sodium-hydrogen exchange function, exacerbating tumor microenvironment acidification and enhancing chemotherapy resistance." (PMID 41235237, 2025). "Additionally, TRPM4 and SLC9A1 were associated with tumor staging: their levels were upregulated in T3-T4 stage BRCA patients compared to T1-T2 stage patients." (PMID 41235237, 2025). "High mRNA expression of SLC9A1 was related to increased numbers of tumor-associated macrophages." (PMID 37298344, 2023). "Increased SLC9A1 mRNA expression was also associated with tumor-associated macrophage accumulation." (PMID 30333031, 2018). "From seven candidate NECSO regulators previously implicated in sodium homeostasis (NC1, CLT, DHPs, SLC12A2, SLC8A1, TRPM4, SLC9A1), intersection analysis identified two NECSO-associated DEGs - TRPM4 and SLC9A1 - showing consistent tumor-specific upregulation." (PMID 41235237, 2025). "SLC9A1 is an important protein in regulating signal transduction, cell migration, pH homeostasis, tumor growth, and cell volume." (PMID 35041720, 2022). "There is a study indicating that in AML, miR-12462 is low-expressed and inhibits AML cell growth both in vivo and in vitro and enhances AML cell chemotherapy sensitivity via targeting SLC9A1, thus playing a tumor-suppressing role." (PMID 36120594, 2022). "The result showed that the SLC9A1 was significantly upregulated in BC tissues in comparison with normal tissues, in addition, SLC9A1 was significantly upregulated in tumor tissues compared with tumor-adjacent tissue of BC." (PMID 34659570, 2021). "The highest SLC9A1 mRNA expression was detected in the tumor region with robust microvascular proliferation, which is consistent with the results of GO terms analysis." (PMID 30333031, 2018). "SLC9A1 mRNA expression was enriched in the tumor area of microvascular proliferation in IVY database." (PMID 30333031, 2018). "The maintenance of pHe/pHi relies on several special proton pumps on tumour cell membranes, such as SLC9A1 and V-ATPase." (PMID 35541713, 2018). "Our biological process analysis reveals that high SLC9A1 mRNA expression was involved in the tumor angiogenesis in both CGGA and TCGA datasets." (PMID 30333031, 2018). "We employed immunohistochemistry to analyze the expression of TRPM4 and SLC9A1 in tumor tissues." (PMID 41235237, 2025). "TRPM4, a sodium-permeable channel, likely drives metastasis through calcium signaling dysregulation, while SLC9A1, a sodium-hydrogen exchanger, may acidify the tumor microenvironment to promote therapy resistance." (PMID 41235237, 2025). "Moreover, genes positive with SLC9A1 mRNA expression were mainly involved in tumor invasion and angiogenesis." (PMID 30333031, 2018). "Mediators of increased acid extrusion in tumor cells include the Na+/H+ exchanger NHE1 (SLC9A1), the Na+,HCO3− cotransporter NBCn1 (SLC4A7), the lactate,H+ cotransporters of the monocarboxylate transporter family, MCT1 and MCT4 (SLC16A1 and −3), and, in some cells, V-type H+-ATPases." (PMID 27266704, 2016). "Interestingly the proton exchange transporter gene NHE1 (SLC9A1) that is important for tumour metastasis was down-regulated, as well as the sodium channel transporters SCN1A, SCNN1B and SCN7A." (PMID 19662092, 2009). "In conclusion, CD44 may interact with SPP1, and SLC9A1 to promote certain tumor progression." (PMID 37316699, 2023). "SLC9A1, also known as Na+/H+ exchanger isoform 1 (NHE1), is a membrane transporter regulating pH in tumor cells, and its main function is to maintain the proton gradient." (PMID 33783998, 2021).
cardiovascular diseases (9 papers, 2013 to 2024). "Downregulation of SLC9A1, associated with methylated DNA sequence, is one of established risk factors in cardiovascular diseases." (PMID 37371794, 2023).
SLC9A1 also shares sentences with these, for which no sentence is quoted: cardiac hypertrophy (37 papers); ischemia (27); diabetes (18); myocardial infarction (12); heart disease (10); Hypertension (9); myocardial ischemia (8); pancreatic cancer (8); cervical cancer (7); hepatocellular carcinoma (7); Arrhythmia (6); breast tumor (6); colorectal cancer (6); infection (6); Myocardial fibrosis (6); prostate carcinoma (6); Cerebral ischemia (5); deafness (5); epilepsy (5); ischemic heart disease (5); atherosclerosis (4); Barrett esophagus (4); colitis (4); endothelial dysfunction (4); left ventricular hypertrophy (4); neurological disorder (4); Sepsis (4); type 2 diabetes (4); Acidosis (3); brain tumors (3).
A further 110 diseases each share a sentence with SLC9A1 in 3 papers or fewer.